AQP4 (aquaporin 4)
Diseases named in the same sentence as AQP4 in open-access papers (continued):
Sharing a sentence is not in itself a finding about the gene and the disease.
cognitive decline (continued). "Experimental models of sepsis underscore AQP4’s involvement in cognitive decline, as AQP4 deletion mitigates memory deficits, reduces neuroinflammation, and downregulates pro-inflammatory cytokines." (PMID 39768394, 2024). "It is known that genetic variation in AQP4 moderates the association between sleep and amyloid-β burden, and, in AD, some specific AQP4 SNPs are related to steeper cognitive decline, whereas others relate to slower progression." (PMID 37693650, 2023). "Serum AQP-4 antibody titers can decrease during disease remission, while obvious cognitive decline in these patients still exists." (PMID 36672071, 2023). "Genetic variations of AQP4 likely alter the glymphatic clearance of Aβ in the brain and subsequently the rate of cognitive decline in PD." (PMID 35356146, 2021). "This occurs together with a reduction of the AQP4 polarization at the perivascular location at the BBB that has been shown previously to correlate with the extent of cognitive decline in AD patients." (PMID 32910547, 2021). "AQP4 rs162009 is likely a novel genetic prognostic marker of glymphatic function and cognitive decline in PD." (PMID 35356146, 2021). "Interestingly in rat models, diabetes has been found to cause glymphatic system dysfunction, reduction in AQP4 density, neuroinflammation, microvascular damage, blood–brain barrier damage and cognitive decline that could be associated with glymphatic system dysfunction." (PMID 32933532, 2020). "They conclude that genetic variations of AQP4 and subsequent alterations of glymphatic efficacy might contribute to an altered rate of cognitive decline in PD." (PMID 36140362, 2022). "Furthermore, evidence indicates that genetic variation in AQP4 modulates sleep quality and architecture, amyloid-β burden and rate and progression of cognitive decline in AD patients." (PMID 36688175, 2022). "Furthermore, AQP4 rs162009 can be considered a novel genetic prognostic marker of glymphatic function and cognitive decline in PD." (PMID 36140362, 2022). "AQP4 rs162009 is likely a novel prognostic marker of cognitive decline in PD." (PMID 35356146, 2021). "Genetic variations of AQP4 and subsequent alterations of glymphatic efficacy might contribute to an altered rate of cognitive decline in PD." (PMID 35356146, 2021). "In this study, using longitudinal data from the Parkinson’s Progression Marker Initiative (PPMI), we tested the hypothesis that AQP4 SNPs were associated with altered CSF or PET biomarker values and rate of motor or cognitive decline in PD." (PMID 35356146, 2021). "In addition, individuals homozygous for either AQP4 SNPS rs3763040-A or rs3763043-A have been reported to experience more rapid cognitive decline after AD diagnosis." (PMID 33134185, 2020). "Interestingly, individuals homozygous for either AQP4 SNPS rs9951307-A and rs3875089-A have been reported to experience slower cognitive decline." (PMID 33134185, 2020). "In AD, AQP4 polarity loss significantly weakens glymphatic clearance, exacerbating Aβ accumulation; Aerobic exercise can restore AQP4 polarization, enhance CSF–ISF exchange, and markedly reduce soluble Aβ levels in AD rodent brains, thereby delaying cognitive decline." (PMID 41459559, 2025). "In the present study, we investigated the short-term effects of uridine on AQP4 dysregulation following SE, and future studies are warranted to identify its long-term consequences within the context of seizure severity, hippocampal sclerosis, and cognitive decline." (PMID 40904734, 2025). "Similarly with the AD, AQP4 SNPs have been associated with some aspects of the clinical course, such as faster cognitive decline, rather than the presence or absence of the disease." (PMID 36688175, 2022). "Genetic variants in AQP4 and APOE4, which influence gene expression and increase the risk of progression to dementia, may help explain individual differences in susceptibility to cognitive decline and dementia in the context of sleep." (PMID 36330347, 2022).
cognitive decline (continued). "Chronic hypoperfusion leads to astrocyte activation, pseudopodia fracture, and decreased expression of aquaporin-4 (AQP4), contributing to BBB breakdown and cognitive decline." (PMID 40277934, 2025). "AQP4 is a CSN water channel involved in part in the glymphatic CSF clearance system and its dysfunction has been correlated with cognitive decline in the elderly." (PMID 35928685, 2022).
encephalitis (36 papers, 2013 to 2025). An acute inflammatory process affecting the brain parenchyma. "However, there are few reports of anti-contactin-associated protein-2 (CASPR2)-related encephalitis, especially with positive anti-aquaporin 4 (AQP4) antibodies." (PMID 37335713, 2023). "Clinicians should consider testing for MOG and AQP4 antibodies when atypical features are present in anti-NMDAR encephalitis patients." (PMID 40611612, 2025). "Many forms of autoimmune meningitis such as GFAP encephalitis, and AQP4 encephalitis can mimic the features of intracranial infection such as TBM, but are naturally unresponsive to antibiotic or antiviral treatment." (PMID 36362480, 2022). "Bien reported a case of paraneoplastic occurrence of antibodies against DPPX and AQP-4 in a patient with breast cancer and encephalitis." (PMID 35382765, 2022). "The autoantibodies assay results supported the diagnosis of overlapped anti-NMDAR encephalitis and anti-AQP4 NMOSD for our patient." (PMID 35527314, 2022). "The other eleven patients developed anti-NMDAR encephalitis and demyelinating features simultaneously (5 anti-AQP4 antibody positive, 2 anti-MOG antibody positive)." (PMID 28698711, 2017). "Recently a case of NMO (seropositive anti-AQP4 Ab) following anti-NMDAR-Ab encephalitis has been described." (PMID 24373538, 2013). "In patients with extensive myelitis who are seronegative for anti-AQP4 Ab, and after other classical causes have been excluded, the hypothesis of atypical anti-NMDAR-Ab encephalitis should also be considered." (PMID 24373538, 2013). "In patients with extensive myelitis who are seronegative for anti-AQP4 antibodies, and after other classical causes have been excluded, the hypothesis of atypical anti-NMDAR-Ab encephalitis should also be considered." (PMID 24373538, 2013). "Previous studies have indicated that symptoms resembling encephalitis, often accompanied by seizures, are more prevalent in MOGAD than in AQP4-IgG NMOSD." (PMID 40740785, 2025). "A 30-year-old woman developed encephalitis a year ago and was diagnosed with NMOSD with serum aquaporin-4 (AQP4) antibody positivity." (PMID 39822442, 2024). "Furthermore, the presence of teratomas has been associated with different antibody-mediated CNS disorders including AQP4 positive NMOSD and anti-NMDAR encephalitis." (PMID 37360349, 2023). "A previous healthy 44-year-old Chinese woman who was followed up for 8 years in the First Hospital of Jilin University developed anti-NMDAR encephalitis coexisting with NMOSD with negative anti-AQP4 antibody in serum and CSF (submission)." (PMID 28698711, 2017). "Subsequent CSF encephalitis panel results showed positive West Nile virus (WNV) IgG but negative WNV IgM, and AQP4 antibodies were positive." (PMID 38046734, 2023).
myasthenia gravis (35 papers, 2010 to 2026). Myasthenia gravis (MG) is a rare, clinically heterogeneous, autoimmune disorder of the neuromuscular junction characterized by fatigable weakness of voluntary muscles. "The two patients with NMOSD had positive AQP-4 antibodies, and the patients with Myasthenia Gravis had antibodies against the receptor for acetylcholine." (PMID 37509537, 2023). "Based on the results of the REGAIN and PREVENT studies, eculizumab is now FDA-approved for refractory AChR IgG-positive myasthenia gravis and AQP4-IgG-positive relapsing NMOSD." (PMID 35043373, 2022). "Myasthenia gravis and NMOSD are caused by the actions of the anti-acetylcholine receptor antibody and the anti-aquaporin 4 antibody, respectively." (PMID 35212290, 2022). "Preclinical studies of AChR IgG-positive myasthenia gravis and AQP4-IgG-positive NMOSD have demonstrated complement-mediated neuronal damage, which was absent with the administration of complement inhibitors." (PMID 35043373, 2022). "These Ab may originate from peripheral antibody-secreting cells after post-germinal centre affinity maturation which then transit into the CNS as seen in AQP4 Ab-associated NMOSD and MuSK Ab-associated myasthenia gravis." (PMID 31481127, 2019). "Following IL-21R–Fc intervention, the frequency of plasmablasts and AQP4-ab levels were significantly reduced, corroborating previous studies in NMOSD and myasthenia gravis." (PMID 41567208, 2025). "Interestingly, several clinical observations have been reported in which patients with myasthenia gravis (MG) also suffer from auto-AQP4-antibody positive NMO simultaneously." (PMID 23270503, 2012). "In addition, 4/26 (15%) patients reported a family history of an immune-mediated condition including MS, AQP4-IgG positive NMOSD, myasthenia gravis, and systemic lupus erythematous." (PMID 37426444, 2023). "In patients with coexisting myasthenia gravis and thyroiditis, the rise in AQP4-IgG levels during disease attack is not connected with any increase in other autoimmune antibodies, for example, to thyroid peroxidase, to thyroglobulin or to acetylcholine receptor." (PMID 26950113, 2016). "AQP4: aquaporin 4; AZA: azathioprine; CP: Cyclophosphamide; RTX: Rituximab; MGCS; Myasthenia gravis composite score; N/A: not administered; MM-3: minimal manifestations." (PMID 33728176, 2021). "(DH) AQP4‐Ab‐positive NMOSD and AChR‐Ab‐positive myasthenia gravis; no clear clinical onset with visual acuity of 0.05 of the right eye with severe atrophy of the optic nerve, additionally, oculomotor symptoms of no definite origin, most probably due to the myasthenia gravis." (PMID 36811295, 2023). "Moreover, several of our AECA-positive patients had very high titers also during remission (similarly, autoantibodies remain detectable during remission in many neurological and non-neurological autoimmune disorders such as AQP4-Ab-positive NMO, myasthenia gravis or SLE." (PMID 24606999, 2014).
Parkinson disease (33 papers, 2012 to 2025). A progressive degenerative disorder of the central nervous system characterized by loss of dopamine producing neurons in the substantia nigra and the presence of Lewy bodies in the substantia nigra and locus coeruleus. "Recent findings have shown that aquaporin-4 (AQP4) deficiency in mice exacerbates alpha-synuclein pathology in Parkinson’s disease animal models." (PMID 39980740, 2025). "Variants of aquaporin-4 (AQP4) which is related to the glymphatic pathway, have been associated with AD pathology in mouse models and in cognitive performance in Parkinson’s disease (PD)." (PMID 37085942, 2023). "Genetic variations, abnormal distribution and quantitative abnormalities of AQP4 have also been associated with several neurodegenerative disorders, such as AD, Parkinson’s disease and amyotrophic lateral sclerosis." (PMID 36688175, 2022). "AQP4 expression pattern deficiency reduced the differential degeneration of mid-brain dopaminergic neurons in experimental Parkinson’s disease." (PMID 32012713, 2020). "Loss of AQP-4 has been reported in Parkinson’s disease and associated with inflammation and in experimental models of breast cancer brain metastases." (PMID 31695842, 2019). "Notably, the Rs2075575 A allele had been described as a risk factor both for NMO patients with anti-AQP4 antibodies and for Parkinson disease in females." (PMID 41009480, 2025). "TGN-020 has demonstrated a reduction in AQP4 polarization in neurodegenerative disease models, including Alzheimer’s disease and Parkinson’s disease, thereby exacerbating glymphatic dysfunctions in which Aβ metabolism plays a crucial role." (PMID 37695472, 2024). "Once depolarization occurs, AQP4 channels migrate to the cell body and prevent effective exchange, which has been observed in various neurological disorders, including AD, Parkinson's disease, intracerebral hemorrhage, and transient focal ischemia 30, 57-59." (PMID 39113801, 2024). "Theories have also found dysregulation of AQP4 to play a pro-inflammatory role contributing to neurological deficits in diseases such as Parkinson’s; thus, the role of AQP4 following closed-head impact TBI is important to study." (PMID 36909284, 2023). "In patients with Parkinson’s disease (PD), the localization of AQP4 in the end-feet of astrocytes is reduced (AQP4 depolarization), manifested as metabolic disorders in cerebrospinal fluid reflux and neurotransmitter clearance related to the impaired glymphatic system." (PMID 40243478, 2025). "According to the authors’ opinion, these results may indicate that AQP4 plays a proinflammatory role in Parkinson’s disease, secondary to the dysregulation of astrocytic volume homeostasis." (PMID 38338949, 2024). "While the evidence of microgliosis and AQP4 expression portends of future problems, it would have been necessary to follow rats to end-of-life (ca. 2.5 years) looking at the major contribution of ageing in Parkinson’s disease." (PMID 34806002, 2021). "The repair of aquaporin-4 polarity, venous compliance, and lymphatic drainage might therefore open new avenues for the diagnosis and treatment of Alzheimer’s and Parkinson’s disease, supplying both biomarkers of disease progression and new targets for early intervention." (PMID 41226584, 2025). "The lack of AQP4 expression in the mouse model of Parkinson disease (PD) was shown to abolish an increase in transforming growth factor-β1 (TGF-β1)." (PMID 33297299, 2020). "However, in cases of Parkinson’s disease, TGN-020 treatment stimulates astrocyte proliferation, which may lead to further reduction of AQP4 polarization." (PMID 37695472, 2024). "Thus, both AQP4 and AQP9 are relevant in the context of Parkinson’s disease." (PMID 33167342, 2020).
dementia (32 papers, 2018 to 2026). Loss of intellectual abilities interfering with an individual's social and occupational functions. "Expression levels of these elements predict dementia status and p-tau levels in the aging human brain and dystrophin-deficient astrocytes have altered astrocyte function and altered AQP4 levels." (PMID 35473943, 2022). "In a prior human post mortem histopathological study, we reported that in the frontal cortex perivascular AQP4 localization declined with age and that this decline associated with dementia diagnosis." (PMID 35473943, 2022). "In patients with PD, AQP4 rs162009 (AA/AG vs. GG) was associated with slower dementia conversion, better performance in letter-number sequencing and symbol digit modalities, lower Aβ deposition in the putamen, anterior cingulum, and frontotemporal areas." (PMID 35356146, 2021). "Previous research on AQP4 rs162009 showed that rs162009_A was associated with PD, and carriers showed slower dementia conversion, better performance in alphanumeric number ordering and symbol digit modalities, and lower Aβ deposition in the putamen, anterior cingulum, and frontotemporal areas." (PMID 37032643, 2023). "Since glymphatic impairment due to AQP4 dysfunction is potentially associated with several neurological disorders such as AD, dementia and traumatic brain injury, enhancing AQP4 functionality might be a promising therapeutic target." (PMID 36920936, 2023). "Adding glymphatic functioning measures, such as MRI-ALPS, circadian BP monitoring, or relevant polymorphisms, such as AQP4, and epigenetic biomarkers in research studies may lead to personalized risk models for dementia and the development of strategies to prevent it." (PMID 37693650, 2023). "In this pilot study, we demonstrated that EPVS, particularly in the CSO, were strongly correlated with AQP4 levels in the CSF in a population of patients undergoing neurological work-up in suspicion of dementia." (PMID 37547746, 2023). "Since perivascular AQP-4 plays a critical role in the clearance of solutes, changes in the AQP-4 channels after a diffuse injury can lead to the progression of dementia in TBI." (PMID 35505702, 2022). "Complementarily to these data, we have found differential patterns of astrocytes implication in dementia using additional markers such as AQP4, GS1, GLAST1, and for ECs such as Lectin UEA, vimentin, PECAM1 and CLDN5." (PMID 34025357, 2021). "Evaluation of this microarray data revealed strikingly consistent associations with the Allen Aging, Dementia, and TBI dataset for each of the four genes (AQP4, DTNA, MLC1, FXYD1)." (PMID 30120299, 2018). "Based on this, we first evaluated the relationship between AQP4 gene expression and dementia status." (PMID 30120299, 2018). "Previous studies have shown that AQP4 rs162009_A carriers have slower dementia conversion, and our results may explain this phenomenon to a certain extent." (PMID 37032643, 2023). "This study proves that a fundamental protein for glymphatic system function and CSF and ISF flow, AQP4, is increased in CSF of patients suffering from different types of dementia compared to healthy controls, and strongly correlates with a marker for established neurodegeneration such as tau." (PMID 36115967, 2022). "These additional gene and protein expression datasets confirm that changes in the expression of AQP4, DAC and candidate endfoot genes and their encoded proteins both predict dementia status and are associated with Alzheimer’s pathology, in particular cortical tau pathology." (PMID 30120299, 2018). "Like the established DAC genes AQP4, DTNA, DAG1 and DMD, expression of several endfoot candidate genes differed between dementia-free and subjects with dementia." (PMID 30120299, 2018).
dementia (continued). "An important observation in the patients with IIH is that the perivascular expression of AQP4 was not reduced, as opposed to the dementia subtype idiopathic normal pressure hydrocephalus (iNPH), which presented with loss of perivascular AQP4 expression." (PMID 35903170, 2022). "No changes in the expression of AQP4 nor any of the 4 DAC genes in the TCX, PCX or FWM significantly predicted dementia status." (PMID 30120299, 2018). "For example, researchers found that before full-blown dementia was observed, people who were non-demented but also scored low on the Mini Mental State Examination (MMSE) or high on the Clinical Dementia Rating Scale (CDR) had a reduction in perivascular AQP4." (PMID 38077948, 2023).